PLEKHG4B (pleckstrin homology and RhoGEF domain containing G4B)
Description:
Guanine nucleotide exchange factor (GEF) which specifically activates small GTPase CDC42 by exchanging bound GDP for free GTP. Plays a role in actin cytoskeletal remodeling in the late stage of cell-cell junction formation by regulating the contractility of actin filaments, which prompts the conversion from 'open' to 'closed' junctions.
Synonyms: KIAA1909; ARHGEF48
Tractability: Antibody: UniProt places it where antibodies can reach, with high confidence; its Gene Ontology location is reachable by antibodies, with medium confidence. PROTAC: ubiquitination databases record sites on it.
Gene: Protein-coding gene on chromosome 5 (92,128 to 189,972, forward strand). Ensembl gene ENSG00000153404.
Subcellular location: Basal cell membrane; Cell junction; Nucleus; Cytoplasm
Subcellular location (Human Protein Atlas): Nucleoplasm
Pathways (Reactome):
Signal Transduction: CDC42 GTPase cycle
Gene Ontology:
Molecular function: guanyl-nucleotide exchange factor activity; protein binding
Biological process: cell-cell adhesion; axon guidance; regulation of small GTPase mediated signal transduction
Cellular component: anchoring junction; basal plasma membrane; cell-cell junction; cytoplasm; nucleus; cytosol; extrinsic component of membrane; plasma membrane
Genetic constraint (gnomAD): Loss-of-function variants: 107 observed, 109.52 expected, observed/expected ratio (o/e) 0.98, 90% interval 0.83 to 1.15. The upper end of that interval is the gene's LOEUF score, 1.15, which puts it in group 5 of 6, group 1 being the genes least tolerant of losing a copy. Missense variants: 1,713 observed, 1,600.1 expected, observed/expected ratio (o/e) 1.07, 90% interval 1.03 to 1.11. Synonymous variants: 697 observed, 658.73 expected, observed/expected ratio (o/e) 1.06, 90% interval 0.99 to 1.13.
Homologues: Orthologues: chimpanzee PLEKHG4B (98% identical), macaque PLEKHG4B (87% identical), rabbit PLEKHG4B (60% identical), dog PLEKHG4B (59% identical), tropical clawed frog KIAA1755 (28% identical), zebrafish si:ch211-269k10.2 (16% identical). Paralogues in human: PLEKHG4 (25% identical), ARHGEF40 (25% identical), TRIO (18% identical), KIAA1755 (17% identical), KALRN (17% identical), MCF2L (14% identical), MCF2 (13% identical), TIAM1 (12% identical), TIAM2 (12% identical), MCF2L2 (11% identical), SPATA13 (9% identical), VAV2 (8% identical), and 10 more.
Diseases named in the same sentence as PLEKHG4B in open-access papers:
PLEKHG4B is named in the same sentence as 4 diseases in open-access papers, as found by Europe PMC text mining. Sharing a sentence is not in itself a finding about the gene and the disease. The quoted sentences say what the papers report.
autosomal dominant spinocerebellar ataxia (1 paper, 2023). "Mutations in the pleckstrin homology domain-containing family g member 4b (PLEKHG4B; puratrophin-1) gene are associated with the hereditary neurological disorder autosomal dominant spinocerebellar ataxia." (PMID 37760246, 2023).
leiomyoma (1 paper, 2023). A well-circumscribed benign smooth muscle neoplasm characterized by the presence of spindle cells with cigar-shaped nuclei, interlacing fascicles, and a whorled pattern. "For comparison of differential expression of genes in leiomyomas, there was a significant race/ethnicity correlation in expression for TNFRSF19, IRS4, PLEKHG4B, PGR, KRT17, CCDC177, MYO5B, and ZNF703." (PMID 37686244, 2023).
cancer (2 papers, 2020 to 2023). A tumor composed of atypical neoplastic, often pleomorphic cells that invade other tissues. "Moreover, there is no research about the association between PLEKHG4B mutations and cancers." (PMID 37760246, 2023). "The function of three genes (UNC79, PLEKHG4B, and ENSCAFG00845007156) and their associations with cancers have not been clearly identified." (PMID 37760246, 2023). "PLEKHG4B was not investigated in any study of cancer, but we speculated that its expression may be positively regulated by LINC00598 because of their PCC of 0.43." (PMID 32149080, 2020).
tumor (2 papers, 2010 to 2023). "The expression of several race-associated genes was also dependent on the MED12 mutation status of the tumor, being higher (FRAT2, TNFRSF19, ACP7, IRS4, PLEKHG4B, KRT17, SLN, and ZNF703) or lower (CAV2) in the mutated specimens compared with wild-type tumors." (PMID 37686244, 2023). "We identified chromosome 5p15.33 as a novel region that was frequently amplified in the tumor tissues and suggest that the PLEKHG4B as showing increased expression." (PMID 20799942, 2010).